BNIP3 (BCL2 interacting protein 3)
Diseases named in the same sentence as BNIP3 in open-access papers (continued):
Sharing a sentence is not in itself a finding about the gene and the disease.
breast cancer (continued). "Here we confirm that bafilomycin A1 (BafA1), a selective vATPase inhibitor, significantly increased death of breast cancer cells in a hypoxia and Bnip3-dependent manner and significantly reduced tumor growth in MCF7 and MDA-MB-231 mouse xenografts." (PMID 24811485, 2014). "In the current study of breast cancers, BNIP3 was highly expressed in the AR-positive group, which corresponded with a previous report of a significant association between BNIP3 expression and AR in prostate cancers." (PMID 25140630, 2014). "BNIP3 is a hypoxia-dependent autophagy inducer and its expression is suppressed in many types of cancer but overexpressed in lung and breast carcinomas." (PMID 25362242, 2014). "Both Bnip3 and Bnip3L/Nix mRNA levels are higher in breast cancer tissue than in normal tissue, and correlated with high-grade status and was associated with more invasive cases." (PMID 22984526, 2012). "BNIP3 expression is lost in a significant portion of invasive breast cancers, which is correlated with poor prognostic features such as positive lymph node status and high proliferation, but not with the hypoxic response." (PMID 19505343, 2009). "Accordingly, the biological function of BNIP3 in breast cancer is controversial." (PMID 39472438, 2024). "BNIP3 is one of the mitophagy receptors playing a suppressing role in breast cancer." (PMID 36937439, 2023). "However, we documented a more rapid induction of the mitophagy marker BNIP3 in the breast cancer cells compared to the keratinocytes." (PMID 37108134, 2023). "However, recent studies have found that TREK1 is overexpressed in prostate cancer (PC) cells, CAV-3 is upregulated in anaplastic thyroid carcinoma, and Bnip3 levels are higher in breast cancer (BC) and NSCLC." (PMID 35805104, 2022). "It promotes leukemic cell transformation and leukemogenesis through inhibiting ATRA (all-trans-retinoic acid)-induced AML (acute myeloid leukemia) cell differentiation and induced malignant characteristics in breast cancer cells by targeting BNIP3 (BCL2 Interacting Protein 3)." (PMID 35923209, 2022). "have proven that FTO could reduce apoptosis in breast cancer cells by inducing BNIP3 mRNA degradation." (PMID 34211849, 2021). "Interestingly, one of the proteins involved in mitophagy, BNIP3, was found deleted in breast cancers, especially in the triple-negative phenotype." (PMID 34830777, 2021). "For example, FTO promoted breast cancer progression by increasing the RNA degradation of the pro-apoptosis gene BNIP3 via m6A demethylation and a YTHDF2-independent mechanism and promoted glioblastoma tumorigenesis and cancer stem cell self-renewal as a component of the m6A regulatory machinery." (PMID 34218271, 2021). "In addition, the eraser FTO is up-regulated in breast cancer where it down-regulates the pro-apoptotic factor BNIP3 to mediate breast cancer proliferation, progression, and metastasis." (PMID 33376192, 2021). "In the breast cancer cell line, BNIP3-induced cell death was blocked by growth factor signaling." (PMID 33207677, 2020). "BNIP3 worked as a good prognostic indicator in pancreatic cancer, indicated poor prognosis in cervical cancer and had inconclusive value of clinical outcome prediction in breast cancer." (PMID 32412667, 2020). "For instance, in a mouse model of mammary tumors, BNIP3 acts as a tumor suppressor." (PMID 33207677, 2020). "BNIP3 was highly expressed in breast cancer, lung cancer, glioma and cervical cancer." (PMID 32412667, 2020). "It was reported that FTO, a key m6A demethylase, was up-regulated and significantly associated with poor prognosis in breast cancer; FTO-reduced m6A modification could promote breast cancer cell proliferation and metastasis by inhibiting BNIP3 expression." (PMID 32766145, 2020).
breast cancer (continued). "Notably, PPARγ is known to upregulate the expression of hypoxia-inducible factor 1 (HIF1), and BCL2 interacting protein 3 (BNIP3) to regulate autophagy in breast cancer cells." (PMID 32244266, 2020). "HIF-1α activates mitophagy in a BNIP3-dependent manner producing a metabolic adaptation that allows cell survival and ROS decrease in a hypoxic environment in MEF cells, and BNIP3 absence in mammary tumor cells increases the Warburg effect, followed by ROS increase and tumor progression." (PMID 31210843, 2019). "Moreover, we also detected that BNIP3 was upregulated in FTO inhibiting or FTO silencing tumor samples in 4T1-hypodermic breast cancer models." (PMID 30922314, 2019). "To determine whether BNIP3 was the main downstream target of FTO to regulate breast cancer initiation and progression, we generated double knockdown (shBNIP3 and shFTO) breast cancer cell lines." (PMID 30922314, 2019). "High BNIP3 activity has been correlated with metastases of breast cancer and colon cancer, while the silencing of BNIP3 may stimulate leukemia, pancreatic, colon and stomach cancer." (PMID 30344951, 2018). "In the current study, we have developed a measles virus armed with BNiP3, pro-apoptotic gene of human origin (rMV-BNiP3) as a therapeutic agent for treatment of breast carcinoma both as a monotherapy and a component of combination therapy based on chemotherapy." (PMID 30697531, 2018). "Moreover, growing evidence has shown that the overexpression of BNIP3 can be detected in many malignancies, such as glioma, breast cancer and prostate cancer." (PMID 27286975, 2016). "The upregulation of Drp1 and BNIP3 was also observed in vivo (human breast carcinomas)." (PMID 27746856, 2016). "Our observation that C-terminal BNIP3 phosphorylation increases in both lung carcinoma and breast cancer cells during nutrient deprivation and hypoxia suggests that the cells might use C-terminal phosphorylation to block BNIP3 cytotoxicity." (PMID 26102349, 2015). "The loss of BNIP3 expression has been correlated with poor prognostic features such as lymph node metastasis, a higher mitotic activity index (MAI), and tubule formation in breast cancer." (PMID 25867717, 2015). "For example, BNIP3-induced activation of autophagy has been described as a mechanism used by transformed cells, including colon carcinoma and breast cancer cells, to promote cell survival, whereas in some breast and glioma cancer cell lines, BNIP3 promotes autophagic cell death." (PMID 26102349, 2015). "Previous studies have done so far as to observe an overexpression of BNIP3 in breast cancers." (PMID 25140630, 2014). "Because the Bnip3 death pathway is so aggressive, we were interested to determine whether it could be induced in hypoxic breast cancer cells by blocking one of the major proton ejection channels thereby disrupting the intracellular pH buffer capability." (PMID 24811485, 2014). "Only a few studies on BNIP3 expression in breast cancer have been published." (PMID 19505343, 2009). "BNIP3 inactivation may therefore be involved in breast carcinogenesis and deserves to be studied as a potential prognostic indicator in breast cancer." (PMID 19505343, 2009). "Furthermore, BNIP3 expression correlated with the mitotic index, which is known to be a strong prognostic indicator in breast cancer." (PMID 19505343, 2009). "Sixteen of the 40 breast carcinomas (40%) were positive for BNIP3 mRNA." (PMID 19505343, 2009). "However, there is controversy concerning the role of BNIP3 in breast cancer progression." (PMID 39472438, 2024). "Moreover, breast cancer patients who are positive for BNIP3 expression exhibit lower rates of axillary lymph node metastasis, while high expression of BNIP3 in node-negative breast cancer patients is associated with a worse prognosis." (PMID 39472438, 2024). "Consequently, downregulating BNIP3 and resulting in reduced apoptosis of breast cancer cells." (PMID 35409166, 2022).
breast cancer (continued). "BNIP3 silencing may be mediated by the lncRNA RP11-317-J19.1, allowing the protein encoded by PTP4A1 to function normally, which may induce the uncontrolled proliferation and migration of breast cancer cells." (PMID 34226298, 2021). "Interestingly, TumorscapeTM (Broad Institute, Cambridge, MA, USA) showed significant deletion around the BNIP3 locus at 10q26.3 in 7 out of 14 human tumor types, including breast cancer while altered sub-cellular localization of BNIP3 in glioma, breast, and prostate cancer has also been reported." (PMID 25810907, 2015). "Notably, our present study demonstrated that silibinin induced MCF7 human breast cancer cells to undergo autophagic cell death (PCD type II), as well as ROS-dependent disruption of ΔΨm and loss of ATP production through a mechanism involving BNIP3." (PMID 25891311, 2015). "However, the majority of breast cancer cells and cancers cells in general may hold the keys to their own demise in the expression of the hypoxia regulated apoptotic protein Bnip3." (PMID 24811485, 2014). "All this implies that BNIP3 expression could be a prognostic indicator in breast cancer." (PMID 19505343, 2009). "Functional studies revealed that FTO promoted breast cancer progression by affecting miR-181b-3p/ARL5B signaling and directly regulating the m6A methylation of 3′UTR of BNIP3 mRNA." (PMID 40002690, 2025). "In breast cancer, FTO mediates m6A demodifications in the 3’UTR of BCL2 interacting protein 3 (BNIP3) mRNA and induces its degradation, promoting breast cancer cell proliferation." (PMID 41373022, 2025). "In the present study, we have used a BNIP3(L)-promoter-eGFP-reporter system to identify and purify mitophagy-high sub-population(s) of MCF7 and MDA-MB-231 breast cancer cells." (PMID 38834039, 2024). "It has been described that over-expression of BNIP3 and BNIP3L occurs in various human solid cancers at early stages, as the tumours become hypoxic, including breast cancers." (PMID 38834039, 2024). "In the case of breast cancer MCF-7cells, we documented a marked increase in the expression of the mitophagy marker BNIP3 after treating the cells with 50 μg/mL ZnO-NRs for 24 h." (PMID 37108134, 2023). "In breast cancer, upregulation of FTO downregulates the m6A epigenetic modification and decreases the expression of BCL2-interacting protein 3 (BNIP3), which is dependent on YTHDF2, a proapoptotic protein." (PMID 36226062, 2022). "In breast cancer, FTO mediated the demethylation of m6A at the 3′-UTR of Bnip3, a pro-apoptotic gene, resulting in YTHDF2-mediated degradation of the Bnip3 transcript." (PMID 35350378, 2022). "BNIP3, a member of the Bcl-2 family, is a target of FTO in breast cancer that mediates cell proliferation and apoptosis." (PMID 35219326, 2022). "AKR1B1, RASGRF2, CRMP1, BNIP3, GSTP1, HOXA5 and PAX6 genes were methylated in ER-positive and HER2-negative breast cancer with ALNM." (PMID 36454866, 2022). "We consulted the Human Protein Atlas Interactive Analysis to validate the expression of the core driver genes, including IDI1, BNIP3, IFRD1, COQ10B, and ZBTB10, at the protein and RNA levels in breast cancer." (PMID 34226298, 2021). "In breast cancer, FTO knockdown increases the level of m6A modification in the 3′-UTR of BNIP3 mRNA and thereby increases its expression, which in turn induces cell apoptosis." (PMID 33926508, 2021). "Our results reveal key genes and lncRNAs, including BNIP3 and RP11-317-J19.1, that are related to breast cancer bone metastasis." (PMID 34226298, 2021). "Tissue microarrays of 76 patients with breast cancer were stained with six IHC markers (MnSOD, Beclin-1, LC3, BNIP3, Parkin, and cleaved caspase 3)." (PMID 34490076, 2021). "In cisplatin‐resistant breast cancer cell line MCF‐7/R, BNIP3 expression was down‐regulated by miR‐944, and inhibition of miR‐944 restored cisplatin sensitivity of MCF7/R." (PMID 32412667, 2020).
breast cancer (continued). "A similar effect has also been observed in the human breast cancer cell line MCF-7 in vitro, where insulin-like growth factor 1 (IGF-1) induces BNIP3 expression in a HIF-1α dependent-manner." (PMID 31121959, 2019). "BNIP3 acts as a tumor suppressor and is negatively correlated with FTO expression in clinical breast cancer patients." (PMID 30922314, 2019). "To verify BNIP3 as a FTO downstream target, we detected both BNIP3 mRNA expression level and protein expression level in breast cancer cells." (PMID 30922314, 2019). "Hypoxia-mediated BNIP3 and LC3BII elevations were likewise repressed by expressing miR-181c in breast cancer cells." (PMID 31078780, 2019). "Further, we identified that BNIP3, a pro-apoptotic member of the Bcl-2 family of apoptotic proteins, was the target gene of FTO in mediating breast cancer proliferation and progression." (PMID 30922314, 2019). "Using an established Drp1 antagonist (Mdivi-1), we treated breast cancer MDA-MB-231 cells and measured the protein levels of BNIP3 and LC3-II." (PMID 27746856, 2016). "Using tissue microarray sections generated from 740 cases of breast cancer, we performed immunohistochemical staining for Glut-1, CAIX, MCT4, ATP synthase, glutaminase, BNIP3, Beclin-1, LC3A, LC3B and p62." (PMID 24020991, 2013). "An increase in non-selective mitophagy through BNIP3 activation has been demonstrated in multiple cancers, including high-grade breast cancer and non-small cell lung cancer." (PMID 37834315, 2023). "In breast cancer, the expression of FTO is up-regulated while that of BNIP3 is down-regulated." (PMID 35141221, 2022). "Therefore, our study identified RHOF, CRMP1, BNIP3 and HOXA5 as novel candidate methylation biomarkers, which can be used to predict ALNM in breast cancer or ER-positive and HER2-negative breast cancer." (PMID 36454866, 2022). "Moreover, in addition to highly methylated AKR1B1, RASGRF2 and CRMP1 gene promoters, BNIP3, GSTP1, HOXA5 and PAX6 gene promoters were also methylated in ER-positive and HER2-negative breast cancer with ALNM." (PMID 36454866, 2022). "Targeted bisulfite sequencing showed that the promoter methylation levels of AKR1B1, BNIP3, CRMP1, GSTP1, HOXA5, PAX6, and RASGRF2 were increased in ER-positive and HER2-negative breast cancers with ALNM, compared with ER-positive and HER2-negative breast cancers without ALNM." (PMID 36454866, 2022). "Furthermore, in addition to highly methylated AKR1B1, RASGRF2 and CRMP1 gene promoters, BNIP3, GSTP1, HOXA5 and PAX6 gene promoters were also methylated in ER-positive and HER2-negative breast cancer with ALNM." (PMID 36454866, 2022). "Similarly, in breast cancer cell line MCF-7, IGF-1 signaling induces BNIP3-dependent mitophagy and turnover of mitochondria." (PMID 33207677, 2020). "To investigate whether BNIP3 mediated FTO-dependent tumor growth and progression, we generated two distinct shRNAs targeting BNIP3 (shBNIP3–1 and shBNIP3–2) in FTO stable knockdown breast cancer cells." (PMID 30922314, 2019). "By analysis of the Oncomine database, we found that BNIP3 was frequently down-regulated in various human cancers including breast cancer comparing to the non-tumor adjunct tissues." (PMID 30922314, 2019). "By immunohistochemistry analysis, we observed dense staining of BNIP3 in invasive carcinomas, which was absent from normal breast tissues, suggestive of upregulated mitochondrial autophagy in breast cancer." (PMID 27746856, 2016). "In contrast to normal breast tissue in which BNIP3 was not expressed up-regulation of BNIP3 was observed in breast cancer." (PMID 27286975, 2016).
breast cancer (continued). "Microarray analysis in breast cancer cells revealed that knockdown of MTDH led to decreased expression of chemoresistance genes ALDH3A1, MET, HSP90, and HMOX1 and increased expression of proapoptotic genes BNIP3 and TRAIL." (PMID 25993398, 2015). "However, while the breast carcinoma MDA-MB-231 and AU565 cells exhibited a transient increase in T188 phosphorylation, T188 BNIP3 phosphorylation increased and remained high during extended hypoxia in lung carcinoma A549 cells." (PMID 26102349, 2015). "For example, Bnip3, a member of the Bcl-2 protein family, induces distinct forms of cell death in different types of cell lines: necrosis of 293T and A549 cells and apoptosis of MCF-7 breast cancer cells." (PMID 24960127, 2014). "Similarly, activation of PPAR-γ induced autophagy in breast cancer cells through upregulation of the HIF-1α protein and BNIP3." (PMID 21179212, 2010). "FTO m6A-mediated demethylation of 3'- untranslated region BNIP3 transcript, which is a proapoptotic protein belonging to the Bcl-2 tumor suppressor family, promoting its degradation via YTHDF2 independent pathways and specific upregulation of BNIP3 retards breast cancer proliferation and metastasis." (PMID 33511112, 2020). "In other words, elevated YTHDF2 expression in FTO silencing breast cancer cells could not inverse the increasing of BNIP3 mRNA expression, indicating the presence of alternative mechanism to stabilize m6A-modified BNIP3 mRNA." (PMID 30922314, 2019). "BNIP3 is not found in normal breast tissue but is up-regulated in breast cancer." (PMID 27286975, 2016). "However, epigenetic silencing is not the likely mechanism of BNIP3 silencing in human breast cancer." (PMID 25810907, 2015). "BNIP3 promoter methylation in breast cancer has however not yet been described." (PMID 19505343, 2009). "Furthermore, in addition to highly methylated AKR1B1, RASGRF2 and CRMP1 gene promoters, BNIP3, GSTP1, HOXA5 and PAX6 gene promoters were also methylated in ER-positive and HER2-negative breast cancer with ALNM, which may serve as candidate methylation biomarkers." (PMID 36454866, 2022). "In addition, BNIP3 was not identified in normal breast but was up-regulated in breast cancer." (PMID 27286975, 2016). "In contrast, only CpG methylation of apoptosis inducer genes BIM and BNIP3, but not of PUMA and NOXA, was relatively high in breast cancer tissues." (PMID 35008411, 2022). "And compared with ER-positive and HER2-negative breast cancers without ALNM, the methylation levels of AKR1B1, RASGRF2, CRMP1, BNIP3, GSTP1, HOXA5, and PAX6 promoter were increased in ER-positive and HER2-negative breast cancers with ALNM." (PMID 36454866, 2022).